HIF1A (hypoxia inducible factor 1 subunit alpha)
Diseases named in the same sentence as HIF1A in open-access papers (continued):
Sharing a sentence is not in itself a finding about the gene and the disease.
tumor (continued). "For instance, hypoxia stimulates HIF-1α- and HIF-2α-dependent expression of ALKBH5, which demethylates NANOG mRNA and increased the percentage of breast CSCs in the tumor microenvironment." (PMID 37015927, 2023). "Tumor-derived lactate drives macrophage M2 polarization and induces VEGF expression in a HIF-1α-dependent manner." (PMID 37740232, 2023). "Intriguingly, compelling evidence has confirmed that hypoxia-driven activation of HIF-1α enhances EMT, which involves in tumor metastasis, immune escape and drug resistance (Saxena, Jolly & Balamurugan, 2020)." (PMID 37426414, 2023). "Hypoxia-inducible factor-1 subunit alpha (HIF-1α), which is overexpressed in the tumor microenvironment and is a substrate of CMA, is involved in cell cycle blockading and enables tumor cells to adapt to hypoxic environments." (PMID 37509689, 2023). "Under hypoxic stress, activated HIF1α enhances the expression of SHMT2 in an MYC-dependent manner, which supports tumor growth by producing NADPH to counterbalance redox stress." (PMID 36755301, 2023). "CSCs, besides their capability to differentiate to ECs, by secretion of factors such as VEGF, HIF-1α, and CXCL12, can promote the recruitment and migration of ECs and mesenchymal stem cells (MSC) to the niche of tumor and differentiation of them into ECs." (PMID 37328876, 2023). "It was verified that the upregulation of HIF-1α, STAT3, and VEGF in tumor cells was likely to enhance the microvessel density and promote the progression of some cancers." (PMID 37333486, 2023). "Curcumol inhibited PD-L1 expression in liver cancer through crosstalk between HIF-1α and p-STAT3 (T705) signaling pathways, restoring cytotoxic T cell activity and the ability to kill tumor cells." (PMID 38155974, 2023). "Sufficient vascularization promoted by HIF-1α and the inflamed milieu of a multicellular TME induce EMT, which, in turn, enables tumor metastasis." (PMID 37583906, 2023). "Severe hypoxia (0.5–2.5% O2) upregulates hypoxia-inducible factor (HIF)-1α, which then activates target genes, including CD44, TGF-β, and cMET, all of which are related to tumor migration and invasion." (PMID 37835592, 2023). "Specifically, SA binds to PHD2 and inhibits its activity, preventing its interaction with the ODD domain of HIF-1α, thereby enhancing HIF-1α stability and promoting tumor angiogenesis by upregulating VEGFA expression." (PMID 37906252, 2023). "Specifically, romidepsin impaired tumor emboli and lymphatic vascular structure, and suppressed the expression of VEGF and HIF-1α in inflammatory breast cancer." (PMID 36969235, 2023). "HIF-1α can enhance cell metabolism under hypoxic conditions and contribute to the activation of VEGF to induce tumor angiogenesis." (PMID 37384288, 2023). "VEGF is a critical pro-angiogenic factor highly expressed in tumour development through the over-activation of STAT3 that, in turn, activates gene expression mediated by HIF-1α." (PMID 37896150, 2023). "In particular, HIF-1α and HIF-2α regulate tumor cell proliferation, migration, glycolysis and angiogenesis via endogenous ROS production." (PMID 37371466, 2023). "The transcription factor facilitates EMT, tumor angiogenesis and chemoresistance by upregulating the expression of key intermediaries such as VEGF, vimentin, HIF-1α and P-glycoprotein." (PMID 37924112, 2023). "It has been revealed that miR-138-5p functions as a tumor suppressor in HCC and suppresses VM by binding to the 3′UTR of HIF-1α mRNA and further downregulating the expression of HIF-1α and VEGFA." (PMID 37274242, 2023). "Conversely, HIF1α has been shown to play an essential role in inducing and maintaining CD8+ T cell effector state functions to enhance CD8+ T-cell-mediated tumour killing." (PMID 37240301, 2023). "Lactate concentration can inhibit the activity of proline hydroxylase (PHD) and weaken the ubiquitination and degradation of HIF-1α by PHD, which indicates that lactate is closely related to tumor metabolism." (PMID 37646027, 2023).
tumor (continued). "These optimized siRNA-loaded CL4H6-LNPs demonstrated efficient uptake by TAMs in the human tumor xenograft mice model, effectively silencing target genes, including STAT3 and HIF-1α genes." (PMID 38258072, 2023). "Histological tumour sections were stained with CD31, hypoxia-inducible factor (HIF)-1α, and carbonic anhydrase IX (CAIX)." (PMID 37166494, 2023). "Since highly hypoxic regions develop in advanced stages of tumour progression, it is noteworthy that significant cytoplasmic colocalization of SUMO2-pH3(Ser10) was identified in HIF1a-positive regions of advanced vs. lower tumour grades." (PMID 36980166, 2023). "In all, HIF-1α upregulated circPDK1, which stimulated c-Myc by regulating miR-628-3p/BPTF signaling and lowering BIN1 to enhance glycolysis and tumor progression." (PMID 37208722, 2023). "Although we performed the IHC analysis to determine the HIF1A protein expression in tissues of PTC and normal thyroid, the role of HIF1A in tumor metastasis and immune cell infiltration require further study in the future." (PMID 36994412, 2023). "Hypoxia inducible factor, a transcription factor, is a heterodimer of the hypoxia inducible factor-1α (HIF-1α) and HIF-1β subunits and has a key role in tumor cells for energy production for maintaining their metabolism." (PMID 36897686, 2023). "HIF-1α and AMPK signaling pathways are major regulators of glycolysis and OXPHOS and are critical for metabolic reprogramming of tumor cells." (PMID 37663261, 2023). "Clinical pathological studies found high levels of cellular signal changes, e.g. HIF1α, HGF and TIMP-2, in the majority of primary tumours and their metastases." (PMID 35953652, 2023). "Hypoxia induced HIF-1α results in increased expression of FOXP3 in Treg cells and at the same time, also promotes CCL28 in the tumor microenvironment." (PMID 37056346, 2023). "Studies have indicated that HIF-1α is overexpressed in AME, suggesting that hypoxia is related to proliferation and invasion of the solid areas of this tumour." (PMID 37559082, 2023). "We show that normal kidney tubules contain weak to strong staining of both HIF-1α and HIF-2α, which was retained in metastatic tumours, different grades, and stages of tumours." (PMID 37174052, 2023). "The expression of HIF-1α increases in the hypoxic tumor microenvironment, and the interaction of HIF-1α with EC cells overexpressing ERRα can enhance the resistance of tumor cells to pyroptosis." (PMID 37864196, 2023). "Accumulation of MDSCs is boosted by HIF-1α, released within the hypoxic condition of TME, to facilitate immune evasion of tumor cells." (PMID 36986550, 2023). "Subcutaneous administration of melittin suppressed NSCLC tumor growth and reduced VEGF and HIF1-α protein expression." (PMID 37513529, 2023). "When neddylation is inhibited in hypoxic conditions (favorable for tumor growth), CRL2 is deactivated, leading to an accumulation of HIF1α and increased stimulation of the HIF1 transcription factor." (PMID 37717015, 2023). "HIF‐1α and HIF‐2α have been reported to play different roles in ccRCC tumor development and inflammation." (PMID 36847128, 2023). "Hypoxia has also been shown to play a crucial role in regulating genes involved in tumor progression, such as VEGF, HIF-1α, and c-Myc, leading to the promotion of angiogenesis, cell growth, and invasion." (PMID 37400960, 2023). "The target genes of miR-21 include PDCD4, SMAD7, PTEN, HIF-1α, KRIT1, and other tumor suppressor genes." (PMID 37316504, 2023). "Among these proteins, knockdown of the IGF2BP3 gene inhibits hypoxia-induced angiogenesis in vivo by downregulating HIF1A, which inhibits angiogenesis mainly by reducing the expression of pro-angiogenic factor (VEGF) in tumor tissues." (PMID 38053093, 2023).
tumor (continued). "Recent studies have revealed oncogenic and tumour-suppressive roles of HIF proteins in ccRCC instigation and propose that modification in the equilibrium of HIF-1α and HIF-2α activities can have a role in ccRCC progression and aggressiveness." (PMID 37174052, 2023). "In our snATAC-seq data, we also observed motifs of HIF1A in the PFKP, ENO2, and HK1 open promoter regions that are more accessible in tumor cells, consistent with the previous reports of HIF1A regulating these genes." (PMID 36973268, 2023). "The experimental results showed that EAA significantly decreased the expression of HIF-1α, VEGF, and N-cadherin proteins in the HT1080 cells, thus inhibiting tumor growth and achieving an inhibitory effect on tumor cell invasion and metastasis." (PMID 36976205, 2023). "Among the tumor tissues, the levels of OCN (p = 0.027) and HIF‐1α (p < 0.001) both showed significant differences between the IBC with MC and the non‐MC groups." (PMID 36971046, 2023). "Tumor tissue showed significantly weak hypoxia green fluorescence 24 h after injection of Pt-tipped Au@ZIF-8 by immunofluorescence staining assay with hypoxia-inducible factor (HIF)-1a, demonstrating that Pt-tipped Au@ZIF-8 could efficiently alleviate tumor hypoxia." (PMID 36632234, 2023). "Using linear regression analysis, we assessed the association of CD20+, CD8+, CD4+, FOXP3+ TIL-subtypes and CD4+/CD8+, FOXP3+/CD8+ ratios with the expression of HIF1α, LDH5, VD (t1, t2 and t3) and VSA (t2 and t3) in the invading tumor front." (PMID 36900270, 2023). "Hypoxia-inducible factor 1α(HIF1α) is a subunit of the transcription factor HIF1, which promotes tumor cell survival and helps to reprogram from oxidative phosphorylation to glycolysis of tumors (the Warburg effect)in response to hypoxia." (PMID 36627705, 2023). "Parkin negatively regulates the expression of HIF-1α and HIF-3α in GBM under hypoxic conditions, resulting in reduced expression of pro-angiogenic factors and tumor invasiveness." (PMID 36980235, 2023). "The HIF-1α signaling pathway mediates the transcription of genes, allowing cells to adapt to hypoxic environments and lead to changes in glycolysis, nutrient uptake, waste handling, angiogenesis, cell death, and cell migration that may promote tumor survival and metastasis." (PMID 37601653, 2023). "Hypoxia‐inducible factor‐1α (HIF‐1α) is often overexpressed in NSCLC, and its silencing has been shown to suppress glycolysis and inhibit tumor growth." (PMID 37584455, 2023). "Accumulation of hypoxia-inducible factor-1 alpha (HIF-1α) can modulate P2X7, increasing invasiveness and stimulating hypoxia tumor angiogenesis." (PMID 35771310, 2023). "Overall, the major driving factors identified here: NO, HIF-1α, and lactate, played a significant role in IFN-γ-signaling-induced tumor growth reduction." (PMID 37965321, 2023). "We then examined if the xenograft model would reproduce the findings on hypoxic markers, and found similar results on immunohistochemical staining with increased HIF-1α, CA-IX, and GLUT-1 staining in the tumor core vs the tumor edge." (PMID 37752585, 2023). "This concept is supported by the fact that while the tumor edge had, as expected, a significantly lower degree of staining for hypoxic markers (HIF-1a, CA-IX, GLUT-1), up to 30% of the cells in the tumor edge still stained strongly for these markers." (PMID 37752585, 2023). "Moreover, under hypoxia conditions, the HIF-1α protein is stabilized together with HIF-1β in the nucleus so that the heterodimer can promote the transcription of many HIF-dependent down-stream target genes that mainly promote tumor cell malignancy, including migration." (PMID 37583906, 2023). "HIF-1α induces epithelial-mesenchymal transition (EMT), which further enhances the ability of tumor cells to tolerate hypoxia, locally invade, infiltrate blood vessels, and survive in peripheral blood vessels." (PMID 37384288, 2023).
tumor (continued). "This increase in MMP13 expression levels was found to be HIF-1α-dependent and induced EMT of the recipient normoxic cell, leading to tumor invasion." (PMID 37292204, 2023). "In addition, increased expression of HIF-1α is a key feature of hypoxic environment, which mediates the transcription of genes related to oxygen transfer and hypoxia metabolic adaptation, and plays an essential role in tumor proliferation, metabolism, angiogenesis, metastasis, and differentiation." (PMID 37400770, 2023). "Under hypoxic conditions, HIF1A expression increases and induces downstream signal pathways, and PI3K -Akt-mTOR signaling pathway can promote tumor proliferation." (PMID 37081097, 2023). "Taken together, RFA combined with other anti-cancer approaches (i.e. sorafenib, transarterial chemoembolization, and chloroquine) exerts a better curative effect in terms of tumor suppression than RFA alone, probably through inhibiting HIF-1α." (PMID 36814489, 2023). "Similar to HIF-1α, VEGF can be induced in response to tumor hypoxia through the HIF pathway or directly secreted by tumor cells." (PMID 37894447, 2023). "Herein, we reported, for the first time, that ESM1 activates the downstream MAPK pathway by binding to the membrane receptor c-Met on the surface of HUVEC cells to promote the production of HIF1α, VEGFA, and MMP9, eventually promoting tumor angiogenesis." (PMID 38201620, 2023). "bLF specifically suppressed tumor angiogenesis through the inhibition of the NF-κB pathway by binding to TRAF6, suppressing p65 phosphorylation, the reduction of HIF-1α and its target gene expressions." (PMID 36678795, 2023). "Previous literature has reported that HIF1α can transcriptionally activate the expression of SPOP, which has tumor-promoting effects in several types of cancer." (PMID 37382594, 2023). "HIF1α is a subunit of HIF1 activated by hypoxia and a key driver of tumor progression in GBM patients." (PMID 37382594, 2023). "Exosomes stimulate tumor angiogenesis affecting the VEGF and HIF-1α expression and by activation of Wnt/β-catenin and NF-κB signaling pathways." (PMID 37448521, 2023). "Various natural agents, such as curcumin, resveratrol, sanguinarine, and ginsenosides, have been shown to inhibit HIF-1α and VEGF expression, thereby suppressing tumor angiogenesis in hypoxic tumors." (PMID 37345074, 2023). "We found significantly positive Pearson R values for the majority of tumor entities, especially regarding correlations between FAP and the angiogenesis-related genes FLT1, KDR, HIF1A, and ETS1." (PMID 36672341, 2023). "It was reported that TRAF6 binds to HIF-1α and increases HIF-1α polyubiquitination, promoting in vivo tumor angiogenesis." (PMID 36678795, 2023). "Our previous studies showed that HIPK2 binds, along with histone deacetylase 1 (HDAC1), to the HIF-1α gene promoter repressing the HIF-1-mediated transcription of many target genes including VEGF, therefore restraining tumor growth." (PMID 36900356, 2023). "Intratumoral hypoxia conditions can activate and stabilize the HIF-1α transcription complex, which regulates Twist or Snail, two key EMT regulators, and, thereby, enhances tumor aggressiveness." (PMID 36814597, 2023). "HIF-1α activity can be regulated by proinflammatory mediators produced by TNBC cells and the hypoxic tumor microenvironment." (PMID 37904441, 2023). "For instance, via HIF-1α and HIF-2α, hypoxia upregulates the expression of immune checkpoints to develop an immunosuppressive tumor microenvironment and facilitate tumor phagocytosis escape." (PMID 37460927, 2023). "As a result, HIF1α downregulates OXPHOS and triggers glycolysis, GLUT1 expression, EMT, and angiogenesis for tumor metastasis in breast cancer." (PMID 38151790, 2023). "On the other hand, HIF1α is destabilized by acetylation, and its deacetylation by HDAC4 maintains higher protein levels and allows it to execute its tumor-promoting functions." (PMID 36901692, 2023).
tumor (continued). "The expression of HIF-1α, ALKBH5, and lymphatic density (LYVE-1 marker) was significantly elevated in tumor tissues." (PMID 36632222, 2023). "The IHC staining of HIF-1α and CD31 that represent hypoxia and vascular cells respectively, also support their enrichment in the first layer of tumor side." (PMID 37337030, 2023). "Despite that, LMP2A-activated PI3K/Akt/mTOR/hypoxia-inducible factor 1-alpha (HIF-1α) also stimulated vasculogenic mimicry formation, which is usually found in advanced stage of tumor." (PMID 37932756, 2023). "Phenotype assays showed that HIF-1α functions as a tumor suppressor and HIF-2α functions as a tumor-promoting factor." (PMID 38085375, 2023). "In particular, HIF1A is stimulates the EMT in cancer cells, and modifies the immune function of tumor cells, and promotes immune escape." (PMID 36816977, 2023). "RMC tumour tissue resembles a high-grade carcinoma exhibiting reticular or cribriform patterns and usually stain positive for VIM, MUC1, pankeratins, PAX8, HIF1α and VEGF8,9." (PMID 37236926, 2023). "Prior to investigation of anti-tumor activity of Ad-CD44-N-HIF-3α4 in MDA-MB-231 (TNBC) cells, we confirmed the expressions of CAR and CD44 on the cell surface and the induction of HIF-1α and VEGF mRNA by hypoxia." (PMID 37064130, 2023). "The interplay of NO, HIF-1α, and lactate in IFN-γ-activated H6 cells reducing tumor growth led us to investigate the effects of these factors in non-NO-producing tumor cells with IFN-γ: CT26 and B16F10." (PMID 37965321, 2023). "This led to an increase in tumor oxygenation levels, as evidenced by T2-weighted magnetic resonance imaging and immunostaining, and the level of hypoxia inducible factor-1α (HIF-1α) and vascular endothelial growth factor (VEGF) in the tumor was down-regulated." (PMID 35624636, 2022). "VEGFA is an angiogenic progenitor, and HIF-1α is an upstream factor of VEGFA and a key effector in the tumor microenvironment, both of which regulate angiogenesis." (PMID 35903690, 2022). "Analyses of these datasets further reveals YB-1, HIF1A, CAIX and G3BP1 transcript levels to be increased in tumours with amplified AKT1 and/or increased AKT1 expression." (PMID 34294889, 2022). "We stained the immunofluorescence sections of all tumor samples, and quantified the fluorescence intensity corresponding to HIF-1α and α-SMA using Image J. HIF-1α and α-SMA were significantly downregulated in the ARS and 231M-AP NPs groups." (PMID 36382024, 2022). "HIF-1α is the most important transcription factor regulating VEGF expression and an essential stimulator of tumor development and metastasis." (PMID 36296726, 2022). "After we treated TAMs from patients either lactate or conditioned medium from two tumor cell lines: the Lewis lung carcinoma (LLC) and the melanoma cell lines, TAMs show enhanced expression of HIF-1α and M2-polarization." (PMID 36038935, 2022). "In summary, our study confirmed the anti-tumor effect of MT1JP on TNBC, and MT1JP inhibited the progression of TNBC possibly by upregulating miR-138 and inhibiting HIF-1α." (PMID 35703312, 2022). "Combined with our previous studies, berberine can deplete tumor polyamines and inhibit ODC expression, ultimately inhibiting tumor growth, reducing intestinal permeability in CRC patients, and downregulating MYC and HIF1α." (PMID 35912204, 2022). "In the tumour cells, cabozantinib interrupts VEGFR1/VEGFR2/c-KIT/TIE2 pathways, downregulating angiogenic factors (HIF1α, VEGFA) and vascular remodelling factors (MMP2, MMP9)." (PMID 35106125, 2022). "The expression of SOX17 and miR-199a was downregulated and that of HIF1α and MALAT1 was upregulated in tumor tissues of mice in the KYSE150R + oe-NC group." (PMID 35614065, 2022). "Overexpression of HIF-1α can promote the production and signal transduction of EMT transcription factors, thus promoting the EMT process of tumor cells and accelerating the invasion, migration, and metastatic ability of tumors." (PMID 36139386, 2022).